MED12L (mediator complex subunit 12L)
Description:
May be a component of the Mediator complex, a coactivator involved in the regulated transcription of nearly all RNA polymerase II-dependent genes. Mediator functions as a bridge to convey information from gene-specific regulatory proteins to the basal RNA polymerase II transcription machinery. Mediator is recruited to promoters by direct interactions with regulatory proteins and serves as a scaffold for the assembly of a functional preinitiation complex with RNA polymerase II and the general transcription factors (By similarity).
Synonyms: KIAA1635; TNRC11L; TRALP; TRALPUSH; NIZIDS; NOPAR
Tractability: PROTAC: ubiquitination databases record sites on it.
Safety:
Unwanted effects reported when the protein is acted on. In parentheses: how it was acted on, where the effect was seen, and who reports it.
neurological events (source: ClinPGx)
Gene: Protein-coding gene on chromosome 3 (151,085,286 to 151,437,072, forward strand). Ensembl gene ENSG00000144893.
Subcellular location: Nucleus
Subcellular location (Human Protein Atlas): Nucleoli
Gene Ontology:
Molecular function: protein binding; transcription coactivator activity; beta-catenin binding; transcription coregulator activity
Biological process: positive regulation of transcription by RNA polymerase II; regulation of transcription by RNA polymerase II
Cellular component: mediator complex; nucleus
Genetic constraint (gnomAD): Loss-of-function variants: 41 observed, 235.01 expected, observed/expected ratio (o/e) 0.17, 90% interval 0.14 to 0.23. The upper end of that interval is the gene's LOEUF score, 0.23, which puts it in group 1 of 6, group 1 being the genes least tolerant of losing a copy. Missense variants: 1,890 observed, 2,431.1 expected, observed/expected ratio (o/e) 0.78, 90% interval 0.75 to 0.81. Synonymous variants: 858 observed, 910.3 expected, observed/expected ratio (o/e) 0.94, 90% interval 0.89 to 1.
Gene-disease validity (ClinGen):
ClinGen rates the evidence that MED12L causes each of these diseases.
Nizon-Isidor syndrome (autosomal dominant): Definitive.
Homologues: Orthologues: chimpanzee MED12L (98% identical), macaque MED12L (96% identical), dog MED12L (96% identical), pig MED12L (96% identical), rat Med12l (95% identical), mouse Med12l (95% identical), rabbit MED12L (90% identical), Drosophila melanogaster kto (40% identical), Caenorhabditis elegans dpy-22 (24% identical). Paralogues in human: MED12 (61% identical).
Diseases named in the same sentence as MED12L in open-access papers:
MED12L is named in the same sentence as 16 diseases in open-access papers, as found by Europe PMC text mining. Sharing a sentence is not in itself a finding about the gene and the disease. The quoted sentences say what the papers report.
Intellectual disability (4 papers, 2020 to 2025). "Although MED12L has been verified to be associated with fetal mental retardation in human, it is also involved in reproductive development." (PMID 33633772, 2020). "Indeed, others report that dysregulation of MED12L is linked to intellectual disability in Nizor-Isidor Syndrome (OMIM 618872) and associated with transcriptional defects." (PMID 41023835, 2025). "Studies have highlighted the relationship between MED12L variants and a range of neurological and developmental symptoms, including intellectual disability, developmental delay, speech disorders, autism spectrum disorders, aggressive behavior, and brain abnormalities." (PMID 41277170, 2025). "MED12L haploinsufficiency is responsible for transcriptional defect and intellectual disability." (PMID 35979430, 2022).
prostate carcinoma (3 papers, 2019 to 2024). A carcinoma that arises from epithelial cells of the prostate gland. "Interestingly, BRCA2-mutant prostate tumors more frequently display amplification of region located on chromosome 3q, encoding the WNT pathway modulator MED12L than sporadic prostate cancers." (PMID 31366128, 2019).
developmental delay (2 papers, 2025). "KMT2A and MED12L, involved in chromatin remodeling and transcription regulation, respectively, are essential for synaptic development and motor–speech coordination, with dysfunctions linked to developmental delays." (PMID 40870030, 2025).
oral cancer (1 paper, 2022).
viral infection (1 paper, 2021). "A recent GWAS study identified a variant within the MED12L gene associated with viral infection response (Epstein-Barr virus (EBV) nuclear antigen (EBNA)) in humans." (PMID 34899750, 2021).
X-linked intellectual disability (1 paper, 2021). An X-linked intellectual deficiency in which not enough information is known, reported or published to indicate whether a gene causes non-syndromic or syndromic presentations. "Moreover, germline variants of MED12 and MED12L also contain large IDR domains, and are found in several genetic disorders associated with X-linked intellectual disability, neuronal and developmental disorders, failure of hematopoietic-specific transcriptional programs, and cancer." (PMID 34683473, 2021).
cancer (4 papers, 2021 to 2023). A tumor composed of atypical neoplastic, often pleomorphic cells that invade other tissues. "MED12L somatic mutations have been identified in both familial and sporadic GC as well as several other cancers." (PMID 34034702, 2021). "MED12L is differentially overexpressed in many cancers however, the MED12L complex is altered in only 3.05% of HNSCC patients." (PMID 37266381, 2023).
MED12L also shares sentences with these, for which no sentence is quoted: deafness (2 papers); autism spectrum disorder (1); genetic disorders (1); leiomyoma (1); leukemia (1); neurological disorders (1); pancreatic cancer (1); speech disorder (1); Uterine leiomyoma (1).